FGF6 (fibroblast growth factor 6)
Description:
Plays an important role in the regulation of cell proliferation, cell differentiation, angiogenesis and myogenesis, and is required for normal muscle regeneration.
Synonyms: HBGF-6; HST2
Tractability: Antibody: its Gene Ontology location is reachable by antibodies, with high confidence; UniProt places it where antibodies can reach, with medium confidence; UniProt predicts a signal peptide or a membrane-spanning region.
Gene: Protein-coding gene on chromosome 12 (4,428,155 to 4,445,815, reverse strand). Ensembl gene ENSG00000111241.
Subcellular location: Secreted, extracellular space
Pathways (Reactome):
Signal Transduction: Downstream signaling of activated FGFR1; FGFR1c ligand binding and activation; FGFR2c ligand binding and activation; FGFR4 ligand binding and activation; FRS-mediated FGFR1 signaling; FRS-mediated FGFR2 signaling; FRS-mediated FGFR4 signaling; Negative regulation of FGFR1 signaling; Negative regulation of FGFR2 signaling; Negative regulation of FGFR4 signaling; PI-3K cascade:FGFR1; PI-3K cascade:FGFR2; PI-3K cascade:FGFR4; PI3K Cascade; PI5P, PP2A and IER3 Regulate PI3K/AKT Signaling; PIP3 activates AKT signaling; Phospholipase C-mediated cascade: FGFR1; Phospholipase C-mediated cascade; FGFR2; Phospholipase C-mediated cascade; FGFR4; RAF/MAP kinase cascade; SHC-mediated cascade:FGFR1; SHC-mediated cascade:FGFR2; SHC-mediated cascade:FGFR4
Disease: Activated point mutants of FGFR2; Constitutive Signaling by Aberrant PI3K in Cancer; Signaling by FGFR1 in disease; Signaling by FGFR2 in disease; Signaling by activated point mutants of FGFR1
Gene Ontology:
Molecular function: protein binding; fibroblast growth factor receptor binding; growth factor activity
Biological process: fibroblast growth factor receptor signaling pathway; positive regulation of cell population proliferation; neurogenesis; positive regulation of MAPK cascade; regulation of cell migration
Cellular component: cytoplasm; extracellular region; sarcolemma
Genetic constraint (gnomAD): Loss-of-function variants: 11 observed, 15.58 expected, observed/expected ratio (o/e) 0.71, 90% interval 0.44 to 1.17. The upper end of that interval is the gene's LOEUF score, 1.17, which puts it in group 5 of 6, group 1 being the genes least tolerant of losing a copy. Missense variants: 248 observed, 262.14 expected, observed/expected ratio (o/e) 0.95, 90% interval 0.85 to 1.05. Synonymous variants: 120 observed, 113.07 expected, observed/expected ratio (o/e) 1.06, 90% interval 0.91 to 1.24.
Homologues: Orthologues: chimpanzee FGF6 (99% identical), macaque FGF6 (98% identical), dog FGF6 (96% identical), rat Fgf6 (94% identical), mouse Fgf6 (93% identical), pig FGF6 (93% identical), rabbit FGF6 (92% identical), guinea pig FGF6 (86% identical), zebrafish fgf6b (63% identical), tropical clawed frog fgf6 (62% identical), zebrafish fgf6a (62% identical). Paralogues in human: FGF4 (50% identical), FGF5 (36% identical), FGF20 (33% identical), FGF9 (31% identical), FGF7 (29% identical), FGF10 (28% identical), FGF16 (28% identical), FGF3 (28% identical), FGF13 (27% identical), FGF22 (26% identical), FGF11 (25% identical), FGF2 (25% identical), and 9 more.
Diseases named in the same sentence as FGF6 in open-access papers:
FGF6 is named in the same sentence as 26 diseases in open-access papers, as found by Europe PMC text mining. Sharing a sentence is not in itself a finding about the gene and the disease. The quoted sentences say what the papers report.
breast carcinoma (3 papers, 2018 to 2022). "In the context of breast cancer, the expression of FGF5 and FGF6 was detected at very low level in comparison with FGF1 and FGF2." (PMID 35193394, 2022). "In contrast to nontreated con cells, for senescent human breast cancer MDA-MB-231 cells, the factors detected by arrays and secreted at a significant level are FGF-6, GM-CSF, IGFBP-1, MCP-1, IL-6, IL-1α, GRO a/b/g, GRO α, IL-8, MIP, MIP-1α, uPAR, ICAM-1, and MMP-1." (PMID 30871042, 2019).
migraine (3 papers, 2020 to 2024). "Furthermore, the subtype analysis in this meta-analysis concluded that migraine without aura (MO) was significantly associated with seven genetic loci: near TSPAN2, TRPM8, PHACTR1, FHL5, ASTN2, FGF6, and LRP1." (PMID 39850553, 2024). "Selectivity for migraine without aura was found for rs1024905 (near FGF6) in combined full and probable migraineurs (pcor = 0.014) but consistent with the null among full migraineurs alone." (PMID 33643179, 2020). "Whereas seven loci (i.e. near TSPAN2, TRPM8, PHACTR1, FHL5, ASTN2, near FGF6, and LRP1) were associated with migraine without aura (in a sample of 8348 cases and 139,622 controls), none were associated with migraine with aura (6332 cases vs. 144,883 controls)." (PMID 32503413, 2020).
myocardial infarction (2 papers, 2022 to 2024). Gross necrosis of the myocardium, as a result of interruption of the blood supply to the area, as in coronary thrombosis. "In a mouse model for myocardial infarction, FGF6 expression was found to be upregulated and associated with a reduction in infarction size and better heart functioning." (PMID 39766329, 2024).
Obesity (2 papers, 2020 to 2021). Accumulation of substantial excess body fat. "In this study, we uncovered a pivotal role of Fgf6 in skeletal muscle metabolism, particularly in humans with obesity and HFD-fed mice." (PMID 34491915, 2021). "Further, overexpression of Fgf6 in the skeletal muscle not only provided partial protection against HFD-induced obesity but also improved glucose and lipid metabolism." (PMID 34491915, 2021). "In this study, we identified downregulation of FGF6 transcript levels and hypermethylation of its promoter region in individuals with obesity after we analyzed sequencing data of skeletal muscle specimens." (PMID 34491915, 2021). "Based on our sequencing analysis, we confirmed the altered expression of FGF6 in the skeletal muscles of individuals with obesity in a larger cohort consisting of 35 pairs of human skeletal muscle specimens." (PMID 34491915, 2021). "FGF6 was hypermethylated in the promoter region and exhibited a decline in gene expression in the skeletal muscle of individuals with obesity." (PMID 34491915, 2021). "The FGF6 promoter is hypermethylated and mRNA levels are decreased in the skeletal muscle of individuals with obesity." (PMID 34491915, 2021). "We found promoter hypermethylation and decreased gene expression of fibroblast growth factor 6 (FGF6) in the skeletal muscle of individuals with obesity using high-throughput sequencing." (PMID 34491915, 2021). "Quantitative reverse transcription PCR (qPCR) results showed that skeletal muscle samples from individuals with obesity exhibited lower FGF6 levels than those from normal-weight participants." (PMID 34491915, 2021). "To address the role of the FGF6/9-FGFR3 pathway in human thermogenic function and obesity, we measured the expression of FGF6, FGF9, and FGFR3 in human adipose tissue biopsies." (PMID 32184391, 2020). "Reduced binding of the cyclic AMP responsive element binding protein-1 (CREB1) to the hypermethylated cyclic AMP response element, which is a regulatory element upstream of the transcription initiation site, partially contributed to the downregulation of FGF6 in patients with obesity." (PMID 34491915, 2021). "Fgf6 in the adipose tissue has recently emerged as a potential therapeutic target in metabolic diseases, and we found that its expression was suppressed in the skeletal muscles of individuals with obesity." (PMID 34491915, 2021). "The development of strategies targeting Fgf6, including DNA methylation editing or AAV gene therapy, can be promising in regulating metabolism in patients with obesity." (PMID 34491915, 2021). "Given the lack of understanding about the functions of FGF6 in skeletal muscle metabolism, we aimed to investigate epigenetic modifications in the FGF6 promoter region and its effects in skeletal muscle specimens of individuals with obesity." (PMID 34491915, 2021).
prostate carcinoma (2 papers, 2005 to 2011). A carcinoma that arises from epithelial cells of the prostate gland. "In prostate cancer, FGFR1 and FGFR4 as well as the ligands FGF-1, FGF-2, FGF-6, FGF-8, FGF-9, and FGF-17 are all known to be over-expressed." (PMID 22078327, 2011). "Overexpression of multiple FGFs (namely aFGF/FGFl, bFGF/FGF2, FGF6 and FGF8) has been identified in prostate cancer." (PMID 15655558, 2005).
bladder cancer (1 paper, 2022). "In bladder cancer cells, linc00265 was found to facilitate cell viability, proliferation and migratory ability via inhibition of miR-4677-3p and promotion of fibroblast growth factor 6 (FGF6) expression." (PMID 35692754, 2022).
cardiac ischemia (1 paper, 2022). "FGF6 treatment significantly improved cardiac function by promoting cardiac repair in mice with cardiac ischemia." (PMID 35355356, 2022).
glioblastoma multiforme (1 paper, 2016). "We detected an FGF6 mutation and four potentially actionable FGFR1 alterations, including one FGFR1 missense mutation, as well as three FGFR1 fusions including a novel FGFR1–HOOK3 fusion and two cases with an FGFR1–TACC1 fusion previously reported in glioblastoma multiforme." (PMID 27974047, 2016).
glioma (1 paper, 2016). A benign or malignant brain and spinal cord tumor that arises from glial cells (astrocytes, oligodendrocytes, ependymal cells). "In the RMPAlow gliomas, a different set of RTK signaling-related genes including MET (8.9%), EPHA1 (8.9%), EPHB6 (8.9%), EPHB4 (8.3%), BRAF (8.9%), FGF6 (11.9%), FGF23 (11.9%), NTF3 (11.9%), and ANGPT1 (9.5%) were amplified." (PMID 27385209, 2016).
Insulin resistance (1 paper, 2021). Increased resistance towards insulin, that is, diminished effectiveness of insulin in reducing blood glucose levels. "In summary, our results suggest that Fgf6 overexpression ameliorates insulin resistance, improves basal oxygen consumption of mitochondria, and increases the AMPK activity of skeletal muscles, enhancing systemic glucose and lipid metabolism." (PMID 34491915, 2021). "Overexpression of Fgf6 in mouse skeletal muscle stimulated protein synthesis, activating the mammalian target of rapamycin pathway, and prevented the increase in weight and the development of insulin resistance in high-fat diet–fed mice." (PMID 34491915, 2021). "We thus hypothesize that a functional adipogenic response is required to efficiently sustain myogenesis after Fgf6 overexpression, without resulting in the development of inflammation or insulin resistance." (PMID 34491915, 2021).
melanoma (1 paper, 2018). A malignant, usually aggressive tumor composed of atypical, neoplastic melanocytes. "We show here that neutrophils responding to early melanoma onset may provide an early source of Fgf1 and Fgf6." (PMID 29666124, 2018).
seminoma (1 paper, 2023). A radiosensitive malignant germ cell tumor found in the testis (especially undescended), and extragonadal sites (anterior mediastinum and pineal gland). "FGF6 (STM: > 70%; GCT: 5%) and FGF23 (STM: > 70%; GCT: 5%) were amplified in the same eight GCT samples (mainly non-seminomas)." (PMID 37726478, 2023).
cancer (10 papers, 2011 to 2025). A tumor composed of atypical neoplastic, often pleomorphic cells that invade other tissues. "These examples are GNRHR, FGF4, and FGF6, which have all been shown to play important roles in cancer biology." (PMID 38555407, 2024). "This resulted in an elevation of FGF6, suggesting abrogation of negative regulation on FGF6 expression by miR-4677-3p, which facilitated the proliferation and metastasis of cancer cells." (PMID 39766329, 2024). "Furthermore, it has been seen that IGFBP-2 may regulate the expression of several potential cancer-promoting cytokines including fibroblast growth factors 6 and 7 (FGF-6 and -7), neurotrophin-4 (NT-4), and placental growth factor (PIGF)." (PMID 22927847, 2012). "The results of our study revealed that FGF6, FGF20, FGF22, and FGF23 are crucial biomarker proteins that NSP-B specifically targets for the therapy of cancer." (PMID 38434705, 2024). "FGF23 and FGF6 have been reported as gained in CRC and other cancer types." (PMID 24367615, 2013).
tumor (9 papers, 2011 to 2023). "Of note, an additional 72-year old male with a T4N1Mx small intestine GIST possessed a FGF6 amplification, among multiple other GAs, potentially having the same functional impact on tumor growth since FGF6 is a reported ligand of FGFR1." (PMID 27974047, 2016). "Upregulated expression of various canonical FGFs (including FGF1, FGF2, and FGF 6–9) derived from tumor cells or stromal cells induces tumor progression in various cancers; however, the effects of circulating hormone-like FGFs (such as FGF19, FGF21, and FGF23) on tumors are unclear." (PMID 31408968, 2019). "Among them, FGF6 and FGF5 are growth factors from the fibroblast growth factors signaling pathway, which are well known players contributing to tumor progression." (PMID 31568528, 2019). "The progressive contextual hepitype methylation and demethylation as seen in FGF6 and HS3ST2 may provide a paradigm for further studies, especially if different tumor entities with the same direction of overall methylation change but a different hepitype pattern are analyzed." (PMID 21750708, 2011).
metabolic disease (1 paper, 2021). A congenital disorder (due to inherited enzyme abnormality) or acquired (due to failure of a metabolically important organ) disorder resulting from an abnormal metabolic process. "Thus, our findings highlight the role played by Fgf6 in regulating skeletal muscle hypertrophy and whole-body metabolism, indicating its potential in strategies aimed at preventing and treating metabolic diseases." (PMID 34491915, 2021).
FGF6 also shares sentences with these, for which no sentence is quoted: colorectal cancer (2 papers); infection (2); adenocarcinoma (1); gastric cancer (1); hemochromatosis (1); leukemia (1); lymphoma (1); migraine without aura (1); Myelodysplasia (1); small intestine (1); systemic sclerosis (1).